CD38 (CD38 molecule)
Diseases named in the same sentence as CD38 in open-access papers (continued):
Sharing a sentence is not in itself a finding about the gene and the disease.
tumor (continued). "Both CD38 and KLRG1 expression on T cells are increased in the TME and up-regulated in human tumor samples after therapies, potentially contributing to adaptive resistance." (PMID 37207205, 2023). "In corroboration with our findings, blockades of CD38 and KLRG1 are being developed as therapeutic strategies to promote tumor immunity and to ameliorate resistance to PD-1/PD-L1 checkpoint inhibitors and other cancer therapies." (PMID 37207205, 2023). "We observed that as compared to PBMC (peripheral blood mononuclear cells), CD8+ T cells at the tumor site exhibited dramatic increase in the expression of PD1, CD38, and Tim3, while Lag3 expression was comparable." (PMID 37566017, 2023). "Our data demonstrated that intratumoral abundance of PD1+CD38+Tim3+ CD8+ T cells was positively correlated with the progression of the disease and highly enriched in NMIBC patients with high tumor burden." (PMID 37566017, 2023). "The current standard-of-care (SOC) for newly diagnosed (NDMM) and relapsed (MMRR) MM patients includes monoclonal antibodies targeting the NAD+-degrading enzyme CD38, thus supporting dependence on a sustained NAD+ biosynthesis also for this tumor." (PMID 36830052, 2023). "have also revealed that when cocultured with MM cells, isatuximab induces NK‐lymphocyte activation beyond tumor‐NK cell cross talk, through increased expression of CD69 and CD137 after Fc binding and CD38 transmembrane signaling." (PMID 37840445, 2023). "Our discovery of CD38 and CD39 expression on the surface of cytotoxic tumor-specific CD4+ T cells will allow the identification and isolation of this cell type for future studies and clinical trials relating to CD4+ T-cell specific immunotherapies." (PMID 36869048, 2023). "For hematologic malignancies, CD33 and CLEC12A (AML), BCMA, and CD38 (MM), and CD30 (PTCL) are targeted as tumor arms." (PMID 36830717, 2023). "CD19, CD20, CD38, CD86 and CD138 detected in tumour tissues were used as markers for positive prognosis." (PMID 36890557, 2023). "The macrophages in these clusters exhibited diverse expression patterns, such as inflammatory marker CD38, as well as ones corresponding to a pro-tumor (CD163, CD204, CD206) and anti-tumor (CD169) phenotype." (PMID 37190141, 2023). "Alternative MM antigens that are being explored as targets for CAR therapy are CD38, SLAMF7, and CD138; however, on-target off-tumor expression of these antigens on other hematopoietic or non-hematopoietic cells compromises their safety profile." (PMID 36850001, 2023). "The regulation of critical signaling molecules involved in T-cell activation, such as CD38 and CD69, further underscores melatonin’s role in modulating T-cell behavior and immune responses within the tumor microenvironment." (PMID 38260850, 2023). "Four days after tumor engraftment, we injected a low dose (1 × 106) of CD38 CAR T cells and measured the tumor burden by weekly bioluminescence imaging." (PMID 37485647, 2023). "A higher proportion of CD38 high B cells in the blood and higher CD40 expression in tumour was prognostic of survival." (PMID 37365284, 2023). "At day 15 post MC17-51 tumor injection, PMN-MDSC from Shp2f/fLysMCre mice had diminished immunosuppressive function and lower expression of CD38." (PMID 36581713, 2023). "This strong ectoenzyme inhibition makes isatuximab more effective in overcoming ADO‐mediated immunosuppression in the MM hypoxic tumor microenvironment, which promotes ADO generation predominantly through the CD38/CD203a/TRACP pathway." (PMID 37840445, 2023). "Both CD38 and CD39 are ectoenzymes responsible for generating extracellular adenosine, which promotes an immunosuppressive tumor immune microenvironment." (PMID 36869048, 2023). "In particular, based on high level of SDC1, TNFRSF17, MZB1, CD38 and low level of CD19 and MS4A1, Cluster 0, Cluster 1 and Cluster 12 were defined as SDC1+ cells, namely plasma cell in HD controls and tumor cells in MM patient." (PMID 36532059, 2022).
tumor (continued). "Functional studies further revealed that #5-CD38-IgG1 was as potent as daratumumab and isatuximab in mediating ADCC and ADCP of CD38-positive tumor cells, while CDC activity was comparable to isatuximab and PCD induction was comparable to daratumumab." (PMID 35784366, 2022). "STI-6643 showed increased macrophage-mediated phagocytosis and anti-tumor activity when combined with anti-PD-L1, anti-CD20 or anti-CD38 mAbs." (PMID 35664753, 2022). "Interferon-β and ATRA are important mediators for the upregulation of CD38 in NSCLC cells, which allows the tumor to develop resistance to anti-PD-L1 and anti-PD-1 treatments." (PMID 35251964, 2022). "Preclinical studies have shown that ATRA-mediated CD38 upregulation can also enhance the immunomodulatory effects mediated by CD38 in AML and CML via reversal of tumor migration and NAD+ mediated resistance mechanisms, respectively." (PMID 36139103, 2022). "For example, circulating MM tumor cells are characterized by lower expression of adhesion molecules (CD138, CD56, CD117, and others) and activation molecules (CD38, CD28, and CD81)." (PMID 35407416, 2022). "CD38-specific HLE-nano-BiKEs that recognize three different and non-overlapping epitopes of CD38 all induced potent cytotoxicity of tumor cell lines in vitro and of primary MM cells ex vivo." (PMID 35651607, 2022). "These Bregs had a CD38+CD1d+IgM+CD147+ phenotype and were induced by IL-21 secreting regulatory T cells (IL-21 expression also being detected within the tumour tissue)." (PMID 35350071, 2022). "Animal experiments have shown that tumor-derived factors such as IL-6, CXCL16, IFNγ, TNFα, and IGFBP-3 positively regulate the expression of CD38, and high expression of CD38 can enhance the immunosuppressive and tumor-promoting capacity of MDSCs." (PMID 36119033, 2022). "We found that higher frequency of Treg and higher co‐expression of HLA‐DR, PD‐1, CD38, TIGIT, and CD45RO were correlated with tumor burden." (PMID 34165864, 2022). "In a concomitant setting SOT101 at 1 nM and the marketed therapeutic anti-CD38 antibody Daratumumab, the anti-CD20 antibody Obinutuzumab or the anti-EGFR antibody Cetuximab at 0.1, 1 and 10 nM were incubated with tumor cells for 20 h." (PMID 36300122, 2022). "All-trans retinoic acid (ATRA) and IFN-β can induce up-regulation of CD38 in tumor cells, and CD38 inhibits CD8+ T cell function through adenosine receptor signaling, thereby making tumor resistant to PD-L1/PD-1 blockade." (PMID 35906622, 2022). "Pharmacodynamic biomarkers were tested for CD38, PD-L1, tumor-infiltrating immune cells, and FOXP3+ regulatory T cells (Tregs) in the tumor microenvironment (TME)." (PMID 35987165, 2022). "Tumour cells resistant to PD-1 blockade produce IFNβ and ATRA (all-trans retinoic acid), increasing CD38 expression on the tumour cell surface." (PMID 35054292, 2022). "Since CD38 is part of the purinergic-signaling cascade that converts NAD+ into immunosuppressive adenosine, the overexpression of CD38 on tumor cells is thought to contribute to an anti-inflammatory tumor microenvironment." (PMID 36405759, 2022). "With the aim of the timely diagnosis of such a form of tumor escape, our approach includes the obligatory examination of CD45, CD38, CD34 and CD24 expression vs. side-scatter (SSC) to find any suspicious cell populations among all nucleated cells." (PMID 36358863, 2022). "The enzyme NPP1 or CD38 produces AMP, and it leads to the production of Ado in the tumor microenvironment through other means, when CD39 activity is lacking." (PMID 35159053, 2022). "Primary MM tumour cells from two patients with RRMM were treated for 72 h, after which the CD38+ CD45− MM cell population was assessed for apoptosis by flow cytometry." (PMID 35159107, 2022). "We used the TIMER database to analyze the differential expressions of CD38, ACE2, BATF2, HLA-DOB, and WARS between various tumor tissues and normal tissues." (PMID 34868310, 2021).
tumor (continued). "As Fas/FasL signaling is the main mechanism of AICD, it can be concluded that ICI therapy, and CD38 upregulation after treatment, seem to be associated with the activation of AICD, which may in turn lead to the depletion of activated cytotoxic CD8+ T cells in the TME and, consequently, tumor growth." (PMID 33467713, 2021). "Overall, we successfully constructed second-generation human ScFv-derived CD38 CAR-T cells and assessed the in vitro functional activity, such as cytolysis and cytokine release, on CD38-positive tumor cells." (PMID 34513682, 2021). "Along with the immunosuppressive adenosine-converting enzymes CD38 and CD39, we also analyzed the expression of PD-1 as an additional important regulator of tumor immune escape." (PMID 34504486, 2021). "Although using the anti-CD38-CAR-T cell has been shown to affect CD38+ MM cells, an undesirable on-target/off-tumor toxicity on CD38+ healthy hematopoietic cells and healthy tissues was reported." (PMID 33781320, 2021). "The tumor-infiltrating CD3+ CD+ T cells and CD38− CD+ T cells have significantly decreased secretion of IFN-γ and Granzyme B compared to paired adjacent normal tissues." (PMID 33934206, 2021). "TAMs co-expressed pro-tumour markers CD204 and CD206, and anti-tumour markers CD169 and CD38, the latter a marker exclusively found upon M1 polarisation in murine macrophages." (PMID 34885021, 2021). "In our study, we also found that tumor-infiltrating CD38+ CD8+ T cells and CD38− CD8+ T cells have significantly decreased of IFN-γ and Granzyme B secretion compared to adjacent normal tissues." (PMID 33934206, 2021). "While in CD38− CD8+ T cells, the expression of PD-1 in tumor and normal tissues was higher than that in peripheral blood, but not increased in tumor-infiltrating CD38− CD8+ T cells compared with CD38− CD8+ T cells in normal tissue." (PMID 33934206, 2021). "Next, we found tumor-infiltrating CD38+ CD8+ T cells expressed higher level of CD103, IFN-γ, TNF-α and perforin than CD38− CD8+ T cells when were reactivated in vitro." (PMID 33934206, 2021). "Using as an example the TAA CD38, we showed that avidity‐specific CARs can be used to construct CAR‐T cells capable of selectively targeting CD38‐expressing tumor versus normal cells." (PMID 33747727, 2021). "It has been recently reported that CD38 expressed on tumor cells of multiple murine and human origins could be upregulated in response to PD-L1 antibody therapy, which led to dysfunction of tumor-infiltrating CD8+ T immune cells due to increasing the production of adenosine." (PMID 34226519, 2021). "Our study also suggests that tumor-infiltrating CD3+ CD+ T cells express a high level of CD103, a demonstrated marker of TRM cells, compared with CD38− CD+ T cells." (PMID 33934206, 2021). "In esophagus cancer, tumor-derived signals such as IL-6, IGFBP3, and CXCL16 trigger the expansion of monocytic MDSCs with increased CD38 expression." (PMID 33727923, 2021). "The specificity and effectiveness of daratumumab treatment were confirmed by a decrease of CD38 expression detected by IHQ and western blot in residual tumor masses, observed only for this treatment." (PMID 33988237, 2021). "In accordance with expectation, we found the expression level of CD38 in CD8+ T cells and the proportion of CD38+ CD8+ T cells in T cells were significantly increased in tumor (T) compared with paired normal lung tissues (N) and peripheral blood (PB)." (PMID 33934206, 2021). "PD-1/PD-L1 blockade has been reported to upregulate CD38, not only on CD8+ cytotoxic T cells, but also on tumor cells." (PMID 33467713, 2021). "There is a CD38+ M1 macrophage population in TME that produces high levels of IL-6 and TNFα with concomitant CD80 expression, prompts more inflammation and helps in tumor suppression." (PMID 33727923, 2021).
tumor (continued). "Moreover, the evaluation of the genetic signature of each tumor and the identification of polymorphisms associated with immune response in patients, especially those involved in IFN-γ and CD38-dependent mechanisms, may provide a relevant tool to identify patients at risk of developing HPD." (PMID 33467713, 2021). "Altogether, the results showed YB1-provoked NK cells were larger, had greater cytotoxicity to tumor cells, and had higher expression levels of CD11b, CD11c, NKG2D, and CD38 compared to the NK cells from PBS-treated mice." (PMID 33953170, 2021). "Plasticity of T cells (defined by higher levels of Tcf1 and lower levels of PD1, CD38, CD101, CD39, and TIGIT) has emerged as a significant factor in their function in vivo in viral and tumor models." (PMID 33320837, 2021). "Other alpha-particle emitters (212Pb, 225Ac and 213Bi) have been evaluated in the framework of CD38-based TRNT and most indicated strong anti-tumour effects." (PMID 34727950, 2021). "In terms of the secretion capacity of IFN-γ, CD38+ CD8+ T cells and CD38− CD8+ T cells in tumor were decreased in IFN-γ secretion than their counterparts in normal tissues." (PMID 33934206, 2021). "In the cytokine secretion experiment, CD38 CAR-T cells secreted proinflammatory cytokines after being stimulated by tumor cells, which promoted the apoptosis of tumor cells." (PMID 34513682, 2021). "In the present study, we also identified CD38-cADPR exhibited a remarkable down-regulation of KEAP1 and upregulation of NRF2 in tumor cells." (PMID 34226519, 2021). "Furthermore, immunosuppressive molecules B7-H3, CD86, and CD38 as well as necroptosome components cleaved caspase-8 and RIP3 (also known as RIPK3) were relatively underexpressed in ASPcKO tumors suggesting less immune surveillance in the tumor microenvironment with Pten loss." (PMID 34535684, 2021). "Thus, lowering CD38 expression may rescue T-cells from tumor-induced dysfunction." (PMID 34070758, 2021). "Then, we found tumor-infiltrating CD38+ CD8+ T cells and CD38− CD8+ T cells both were decreased in the secretion of Granzyme B compared with normal tissue and peripheral blood." (PMID 33934206, 2021). "To evaluate the antitumor effect of CD38 CAR-T cells in vivo, we established tumor xenotransplantation models by i.v. injection of RPMI-gfp-luc tumor cells." (PMID 34513682, 2021). "It was still possible to expand fully cytotoxic CD38-CAR iNKT cells by stimulation with α-GalCer loaded DCs, even if they had been stimulated for 6 weeks only with tumor cells." (PMID 33499253, 2021). "And in CD38 LLC-bearing-BALB/c-nude mice tumor tissues, it was also confirmed that CD38 KO and MU-bearing-tumor tissues exhibited a higher expression of Keap1 than that of in CD38 WT and OE-bearing-tumor tissues." (PMID 34226519, 2021). "These TMMs secrete IL-1, basic fibroblast growth factor, VEGF, and regulate Ca++ mobilization via CD38 mediated cADPR, contribute to TMM activation, angiogenesis, and immunosuppression, thus helping in tumor progression." (PMID 33727923, 2021). "Next, triple staining of BMNCs (CD38, CD138, and annexin V) followed by flow cytometry analysis showed that the percentages of annexin V+ non tumor cells were unchanged after 5,6 α-EC, 5,6 β-EC, or vehicle-treatment (18.8% and 18.4% vs. 17.9%)." (PMID 34359648, 2021). "The anti‐CD38 CAR‐T cells thus selected displayed robust antitumor efficacy both in vitro and in vivo, with minimal on‐target off‐tumor effects." (PMID 33747727, 2021). "In this study, it was confirmed that CD34+CD38− cells from AML patients possess strong LSC characteristics and tumor formation potential." (PMID 34295821, 2021). "It is interesting that tumor-infiltrating PD-1+ CD3+ CD+ T cells expressed higher levels of both CD69 and HLA-DR than tumor-infiltrating PD-1+ CD38− CD+ T cells." (PMID 33934206, 2021).
tumor (continued). "To evaluate this characteristic in our anti‐CD38 CAR‐T cell constructs, we examined their level of cytotoxicity toward tumor cells overexpressing CD38 as compared to normal cells with physiological levels of CD38 expression." (PMID 33747727, 2021). "The bystander memory TIL population also contained a significantly lower frequency of CD38 and CD101 double-positive cells compared to the tumor-specific T cells, thus indicating that bystander memory cells in the TME are resistant to terminal differentiation." (PMID 34867942, 2021). "In HCC, we observed increased expression of several more activation- (IFNG, CD38, IL2RA, TNFRSF9) and exhaustion-related (TIGIT, CTLA4, PDCD1, ENTPD1) genes in tumor MAIT cells." (PMID 32849590, 2020). "K562-IR cells are CD34-/CD38-, BCR-Abl-independent, proliferate slowly, highly adherent and form intact tumor spheroids." (PMID 32106243, 2020). "We show that the treatment of NSCLC spheroids with Peptide R, besides preventing tumor cell dissemination, decreases expression of immunosuppressive molecules, such as CD73, CD38, and IL-10." (PMID 33123122, 2020). "However, CD38 has also been reported to be expressed in non-hematopoietic tissues, e.g., the gastrointestinal tract or cerebellar Purkinje cells, which is associated with on-target off-tumor toxicity." (PMID 32659909, 2020). "The next step was to utilize the optimal formulations of CD38- and CD138-targeted nanoparticles to deliver doxorubicin pro-drug to the tumor." (PMID 33138841, 2020). "Tumor-infiltrating MAIT cells highly expressed CD69, CD103, CD38, and CD39 with lower expression of CD27 and CD49d compared with peripheral MAIT cells." (PMID 33205061, 2020). "The relevance of CD38 as a biomarker of clinical aggressiveness in CLL is well known, and its role in tumor homing and proliferation has been elucidated in recent years." (PMID 32225002, 2020). "An increasing trend with advanced tumor stage and the percentages of CD8+ HLA‐DR/CD8+ T cells (F = 4.838, P = .001) and CD8+ CD38+/CD8+ T cells (F = 5.984, P < .001) was shown in this study." (PMID 32459060, 2020). "An increasing trend with advanced tumor stage and the percentages of CD8+ HLA‐DR/CD8+ T cells and CD8+ CD38+/CD8+ T cells was shown in this study." (PMID 32459060, 2020). "Bispecific CAR-T cells targeting BCMA and another tumor-specific antigen such as CD19 and CD38 have recently been developed to improve clinical efficacy by reducing the risk of relapse due to antigen escape." (PMID 32943087, 2020). "CD38 is expressed at high levels in most cases of DLBCL, with an average of 80% positivity detected across various tumor specimens." (PMID 32225002, 2020). "The identification of CD38 as a key modulator of NAD+ metabolism in the context of cell signaling, aging, and tumor biology suggests that the enzyme is a target of promising therapeutic potential." (PMID 31214171, 2019). "In multiple murine models, genetic manipulation of CD38 on the tumor cells, or treatment with either small molecule inhibitors or an anti-CD38 antibody, regulated tumor growth in a CD8 T cell-dependent fashion and produced a broader anti-tumor immune profile." (PMID 31878283, 2019). "This emphasizes the importance of understanding the roles of factors such as CD38 and CD157, which are involved in immunosuppression, to successfully predict and alter the immune response to various types of tumor." (PMID 31861847, 2019). "Flow cytometry confirmed the tumor-specific presence of activated (CD4+PD-1++CD161−CD38+HLA-DR+ and CD8+CD103+CD161−NKG2A+/−PD1++CD38++HLA-DR+) effector memory T cells." (PMID 31481117, 2019). "We also discuss the paradoxical role of CD38 as a modulator of intracellular NAD+, particularly in tumor immunity." (PMID 31214171, 2019).